APOE (apolipoprotein E)
Diseases named in the same sentence as APOE in open-access papers (continued):
Sharing a sentence is not in itself a finding about the gene and the disease.
atherosclerosis (continued). "Our results confirmed that vascular endothelial cell‐specific knockout of GRK2 reduces atherosclerosis in ApoE‐/‐ mice fed a high‐fat Western diet." (PMID 40492401, 2025). "ApoE–/– Listerinfl/fl Lyz2Cre mice and ApoE–/– Listerinfl/fl mice were fed a WD for 16 weeks and were then euthanized and evaluated for atherosclerosis." (PMID 40526435, 2025). "ApoE−/− mice are the ideal model for the study of atherosclerosis and also one of the most used mouse models in the field." (PMID 40383150, 2025). "Another study showed that Aucubin improves atherosclerosis in ApoE-/- mice by modulating gut microbiota, particularly by increasing indole-3-acrylic acid (IAA)." (PMID 40356907, 2025). "Yao, X., Cheung, W.T., Ying, F., Zhang, Y., Meng, Z. (2021): TRPM2-based peptide vaccine against atherosclerosis in ApoE knockout mouse model." (PMID 40266108, 2025). "Taken together, these results demonstrated that circ‐PIAS1‐5 activates the AMP‐activated protein kinase pathway by regulating TEAD1 and contributes to atherosclerosis in ApoE−/− mice." (PMID 40089857, 2025). "In aggregate, these data indicate that rmSIRT1 delivery restores systemic SIRT1 levels and blunts molecular signatures of atherosclerosis thereby promoting atheroprotective effects in ApoE−/− mice." (PMID 40653676, 2025). "In experimental studies of atherosclerosis, ApoE-/- mice are among the most commonly used transgenic models." (PMID 40444232, 2025). "Apolipoprotein E (ApoE) plays a crucial role in lipid clearance, and its dysregulation can contribute to the development of atherosclerosis and cardiovascular disease." (PMID 40444232, 2025). "For translational research, immediate next steps include evaluating the in vivo efficacy of stir-fried Perilla extracts in atherosclerosis animal models (e.g., ApoE−/− mice) to confirm lipid-lowering and plaque-stabilizing effects." (PMID 41182513, 2025). "The ApoE-knockout mouse represents the standard experimental model for studying atherosclerosis and endothelial dysfunction." (PMID 41465167, 2025). "In atherosclerosis, AIM2 and its ligand dsDNA are increased in macrophages at advanced disease stages in HFD fed ApoE‐deficient mice." (PMID 39158380, 2025). "Bone marrow transplantation studies in mice further demonstrate the protective role of macrophage-derived apoE against atherosclerosis, highlighting the intersection between systemic lipid metabolism, vascular health, and dementia risk." (PMID 40275327, 2025). "In ApoE−/− mice fed with high‐fat diet, luteolin substantially reduced atherosclerosis by reducing inflammation." (PMID 39830909, 2025). "Even a single injection of the adenoviral vector encoding SAA1, resulting in only a brief elevation of circulating SAA, was sufficient to increase atherosclerosis in apoE-/- mice in the immune-tolerant recombination activating gene-1-deficient background." (PMID 40429677, 2025). "In this study, we identified and characterized a novel circ‐PIAS1‐5 (lipid‐related factor sequence) as an essential regulator of foam lipid accumulation in atherosclerosis in apolipoprotein E knockout (ApoE−/−) mice." (PMID 40089857, 2025). "Transgenic mice carrying APOL1 (G0 and G1 variants) on bacterial artificial chromosomes (BAC/APOL1 mice) were crossed with the apolipoprotein-E knock-out (ApoE-KO) dyslipidemia and atherosclerosis mouse model." (PMID 40459058, 2025). "A few studies found that atherosclerosis was reduced in ApoE−/− mice when treated with L. acidophilus (ATCC 4356 and 4962), L. rhamnosus GR-1 and A. muciniphila." (PMID 40741383, 2025).
atherosclerosis (continued). "MiD49/51 expression was elevated in aortic valve ECs from ApoE−/− mice with high-fat diet-induced atherosclerosis, which accelerated DRP1-mediated mitochondrial fission." (PMID 40093324, 2025). "A previous report suggested that SAA3 is proatherogenic in male ApoE-/- mice, as evidenced by worsened atherosclerosis when Saa3 was overexpressed and by improved atherosclerosis when Saa3 was silenced." (PMID 40083551, 2025). "Considering the great potential of celastrol in the treatment of inflammation-associated diseases, the efficacy of celastrol-enriched peanut on atherosclerosis was investigated in a mouse model of atherosclerosis (ApoE−/− mice) fed a 10-week high-fat diet." (PMID 40362727, 2025). "Whole aortas of ApoE−/−Hm13mKO→ApoE−/− chimeras exhibited less atherosclerosis, and those of ApoE−/−Hm13mOE→ApoE−/− chimeras exhibited enhanced atherosclerosis, relative to ApoE−/−Hm13fl/fl controls." (PMID 40112173, 2025). "ApoE stimulates synthesis of macrophages M2 markers (as arginin-1) which, in contrast to M1 type, determine a reduction in atherosclerosis and inflammation." (PMID 41465167, 2025). "In this study, we show that ANRIL overexpression causes atherosclerosis in vivo as transgenic mouse overexpression of full-length ANRIL (NR_003529) increases inflammation and aggravates atherosclerosis under ApoE−/− background (ApoE−/−ANRIL mice)." (PMID 40383150, 2025). "ALW-II-41–27 significantly alleviates atherosclerosis in ApoE-/- mice by reshaping gut microbiota and modulating bile acid metabolism, reducing plaques and increasing collagen and smooth muscle cell content." (PMID 40356907, 2025). "Alzheimer's disease (AD) and atherosclerosis (AS) are age-related inflammatory conditions with shared drivers such as distinct apolipoprotein E (ApoE) allotypes, oxidative stress, and inflammation." (PMID 40637922, 2025). "The research investigated a high-fat diet and interventions with LGG or telmisartan on atherosclerosis in ApoE-/- mice, finding both LGG and telmisartan significantly reduced atherosclerotic plaque size and improved various biomarkers." (PMID 40356907, 2025). "To circumvent this issue, we previously generated apolipoprotein E–deficient mice with ubiquitous progerin expression (Apoe−/−LmnaG609G/G609G), which developed excessive high‐fat diet‐induced atherosclerosis compared with progerin‐free Apoe−/− controls." (PMID 39479939, 2025). "A study was conducted to assess the impact of a high-fat diet on LncRNAs in an atherosclerosis ApoE(−/−) mouse model." (PMID 40944193, 2025). "It has been demonstrated that cinnamaldehyde and cinnamon treatment leads to downregulation of the NF-κB pathway and reduces the levels of proinflammatory cytokines in diseases such as T2D and atherosclerosis in ApoE−/− mice." (PMID 40216734, 2025). "Unexpectedly, GF ApoE−/− mice, with higher plasma and hepatic cholesterol levels, developed less atherosclerosis than conventionally raised (Conv) ApoE−/− fed a control diet (early atherosclerosis model)." (PMID 39957996, 2025). "The three most promising proteins (CELSR2, FN1, and SPARCL1) were identified as potential therapeutic targets for atherosclerosis, while APOE, LPA, APOA5, TGFB1, and AGER also hold potential as drug targets for the disease." (PMID 40649979, 2025). "In both ApoE-deficient mice and macrophages, decreased EC-SOD levels were shown to lead to higher O2− concentrations, aggravating atherosclerosis." (PMID 39898976, 2025). "Apolipoprotein E knockout (ApoE−/−) mice were used as a model of atherosclerosis; we found that hesperidin treatment improved physiological and metabolic health, reduced plaque formation, and decreased systemic inflammation and oxidative stress." (PMID 41154096, 2025). "Oil Red O staining results showed that CACN136 significantly improved atherosclerosis plaques in the aorta and aortic root of ApoE-/- mice." (PMID 40635740, 2025).
atherosclerosis (continued). "In this study, female ApoE−/− mice were used as the animal model to investigate the influence of sex on the progression of atherosclerosis." (PMID 40611318, 2025). "Overall, ApoE−/−P-Jak2 KO mice displayed increased plaque burden in the aortic arch and root as shown by increased plaque area in both early and late phases of atherosclerosis." (PMID 40825505, 2025). "Applying a model of Apolipoprotein e-deficient (Apoe–/–) mice combined with either Mif-2 deficiency or pharmacological MIF-2 blockade, we investigated the role of MIF-2 in atherosclerosis." (PMID 40055309, 2025). "In this study, the atherosclerosis models of lipid deposition at the whole aorta were constructed successfully using apoE−/− mice fed with an HFD." (PMID 41464973, 2025). "These viruses, alongside control viruses, were delivered to ApoE–/– mice fed a WD to establish an atherosclerosis model." (PMID 40526435, 2025). "We recognize that our study did not address potential mutant GR effects on apolipoproteins (e.g., ApoE itself) or macrophages, both critical determinants of atherosclerosis and in turn regulated by glucocorticoids and/or GR." (PMID 40591411, 2025). "The samples for these studies originated from human carotid or aortic plaques, as well as various atherosclerosis animal models such as ApoE−/− mice and atherosclerosis rat models." (PMID 40563948, 2025). "In summation, we have demonstrated that systemically bioavailable butyrate dosed through SerBut is able to modulate immunity, thus suppressing atherosclerosis progression and liver pathology in the ApoE–/– HFD murine model of atherosclerosis." (PMID 40779455, 2025). "Atherosclerosis was reduced in remdesivir-treated mice along with decreased VCAM-1 expression in aortic roots of ApoE −/− mice, which indicates potential anti-inflammatory effects of remdesivir." (PMID 40598260, 2025). "Colonization of atherosclerosis-prone ApoE–/– sterile mice with Roseburia reduces inflammatory markers and ameliorates atherosclerosis." (PMID 40202300, 2025). "The mRNA and protein expression of TGF-β, PPAR-γ, LXR-α, and ABCA1 in aortic and liver of atherosclerosis apoE−/− mice were upregulated (p < 0.05, p < 0.01), while those of PI3K and Akt1 were suppressed (p < 0.05, p < 0.01)." (PMID 41464973, 2025). "Targeted silencing of BAF60a in ApoE-KO mice highlights its potential as a therapeutic target in atherosclerosis, offering a novel strategy to simultaneously modulate lipid metabolism and vascular inflammation for plaque stabilization and regression." (PMID 40641605, 2025). "Concurrent with the high‐fat diet, ApoE−/− mice were intravenously injected with psEVs twice a week for 8 weeks to evaluate their impact on endothelial inflammation and atherogenesis on the atherosclerosis background." (PMID 40391195, 2025). "In a model of hyperhomocysteinemia (HHcy)-accelerated atherosclerosis in ApoE−/− mice, B cells (Cd79a, C79b, Cd19) were found to be the most abundant leukocyte population (47.2%), together with macrophages." (PMID 40497946, 2025). "As expected, in atherosclerosis, ApoE−/− mice fed a HF/HC diet supplemented with propionic acid developed less atherosclerotic plaques than those that were not supplemented due to increased Treg cell numbers and lL-10 levels in the gut microenvironment." (PMID 39957996, 2025). "On the other hand, macrophage-specific Jak2 KO mice are protected against high-fat diet–induced systemic insulin resistance, obesity, and inflammation, but paradoxically also show increased atherosclerosis in an ApoE-null model." (PMID 40825505, 2025).
atherosclerosis (continued). "Hydroxyurea effectively mitigates atherosclerosis in ApoE-/- mice by modulating gut microbiota and cholesterol metabolism, reducing plaque and liver lipid accumulation." (PMID 40356907, 2025). "SFRP4 alleviates atherosclerosis in ApoE−/− mice by reducing inflammation and oxidative stress and acting via the Wnt/β-catenin signaling pathway." (PMID 40362725, 2025). "Deficiency or abnormality of ApoE causes hyperlipoproteinemia type III, which is characterised by early atherosclerosis and cholesterol accumulation in the blood." (PMID 40026711, 2025). "In ApoE KO mice, trehalose decreased the development of atherosclerosis and enhanced cardiac remodeling following myocardial infarction." (PMID 40354374, 2025). "Taken together, these findings demonstrate that GE can alleviate high‐fat diet‐induced atherosclerosis in ApoE−/− mice by inhibiting oxidative stress‐induced endothelial cell apoptosis and inflammation." (PMID 40718724, 2025). "Research table myriocin can ameliorate atherosclerosis in ApoE−/− mice by reducing lipid uptake and vascular inflammation." (PMID 39920588, 2025). "For example, overexpression of DNMT1 was associated with the repression of PPARγ activities, leading to increased macrophage inflammatory responses and accelerating the accelerated atherosclerosis development in ApoE-/- mice." (PMID 40857741, 2025). "Using 16S rRNA sequencing and histological techniques, we deeply explored the therapeutic mechanisms of T-K for atherosclerosis in the ApoE−/− mice model." (PMID 41244676, 2025). "Apolipoprotein E (ApoE) and monocyte chemoattractant protein-1 (MCP-1) are inflammatory markers associated with premature atherosclerosis, which leads to increased cardiovascular disease risk among people with HIV (PWH)." (PMID 41541874, 2025). "This means KMUP-1 possesses a proautophagy effect by targeting Atg7 protein activation against atherosclerosis in HFD-fed ApoE-KO mice." (PMID 41194853, 2025). "Thirdly, the ApoE-/- mouse model has been widely accepted for studying atherosclerosis and cardiovascular disease, despite its limitations in fully replicating the LDL-driven pathology of FHC." (PMID 41567222, 2025). "In ApoE-/- mice, Roseburia intestinalis interacts with dietary plant polysaccharides to improve gut metabolism and reduce atherosclerosis, revealing gut microbiota and diet interaction mechanisms." (PMID 40356907, 2025). "This DTX administration protocol was therefore used to investigate the effects of DTX on atherosclerosis in ApoE−/− mice." (PMID 40003949, 2025). "In another work, a murine model of atherosclerosis with HHcy was created by supplying L-Met (1 g/kg dissolved in drinking water for 16 weeks) to ApoE−/− mice." (PMID 40650206, 2025). "In the ApoE−/− mouse unilateral carotid artery ligation model of atherosclerosis, MMSN@NAR demonstrated marked accumulation in plaques and excellent biocompatibility." (PMID 40927137, 2025). "Although the present work focused on in vitro mechanisms, further in vivo studies using atherosclerosis models, such as ApoE-knockout mice, would be valuable to support this mechanism." (PMID 41303456, 2025). "In atherosclerosis, commonly used animal models, such as LDL receptor-KO mice and apolipoprotein E-KO mice, take weeks or months to develop, whilst human atherosclerosis typically progresses over decades." (PMID 40429915, 2025). "For instance, ApoE-null mice with myeloid-specific Jak2 deletion develop accelerated atherosclerosis despite being protected against high-fat diet–induced obesity, systemic insulin resistance, and inflammation in liver and visceral adipose tissue." (PMID 40825505, 2025). "A limitation of the present study is that only the ApoE−/− mouse model was employed to investigate the role of SENP3-mediated DeSUMOylation of CCL17 in atherosclerosis." (PMID 41266856, 2025).
atherosclerosis (continued). "Compared to the blank group of mice, the levels of inflammatory factors IL-6 and TNF-α were significantly elevated in the ApoE−/− model group of mice with atherosclerosis." (PMID 40635740, 2025). "Disulfiram reduces atherosclerosis in ApoE-/- mice by inhibiting GsdmD, inducing autophagy, and modulating gut microbiota." (PMID 40356907, 2025). "One study demonstrated that skeletal muscle-derived EVs alleviated atherosclerosis though reducing the plaque size and number in aorta in the ApoE-/- mice, whereas exosomal inhibitor GW4869 counteracted the protective effects." (PMID 40386050, 2025). "The lack of difference in platelet stimulation by ADP, FIIa, and collagen suggests that the increase in atherosclerosis observed in ApoE−/−P-Jak2 KO mice are likely attributable to other factors than the mechanism of integrin αIIbβ3 activation." (PMID 40825505, 2025). "While the ApoE−/− model is the classical tool for atherosclerosis research, we explicitly acknowledge the inherent species-specific differences in metabolic, inflammatory, and plaque stability profiles compared to human pathology." (PMID 41458991, 2025). "In this study, we investigated the impact of KMUP-1 on atherosclerotic lesions, inflammation, autophagy, and cardiac remodeling, as well as lipid metabolism indexes in an animal model of atherosclerosis, ApoE-KO mice, fed with an HFD." (PMID 41194853, 2025). "When constructing atherosclerosis models using ApoE−/− mice, additional cholesterol is typically required." (PMID 40169541, 2025). "The most important observation of the present study was that KMUP-1 attenuated atherosclerosis development in ApoE-KO mice fed an HFD by restoring impaired autophagy." (PMID 41194853, 2025). "In this study, we investigated if GE has protective effects against high‐fat diet (HFD)‐induced atherosclerosis in ApoE−/− mice, which is a widely used mouse model of atherosclerosis." (PMID 40718724, 2025). "Although there were no obvious changes in body weight, food intake, and blood glucose at 2, 3, and 4 months after treatment, the results definitely showed that 4 months of both NMN2 and NR2 treatments also aggravated atherosclerosis in HFD-fed ApoE−/− mice." (PMID 40143060, 2025). "Another study reports that exosomes ameliorated atherosclerosis in ApoE−/− mice and promoted M2 macrophage polarization in the plaque via the miR-let7/HMGA2/NF-κB pathway." (PMID 39866781, 2025). "Recombinant Nef injection accelerates atherosclerosis in ApoE−/− mice by worsening dyslipidemia and inflammation." (PMID 40237461, 2025). "To analyse the contribution of AnxA8 in the progression of atherosclerosis, we bred AnxA8−/− mice with the atheroprone mouse model, ApoE−/−, to generate ApoE−/−AnxA8−/− mice." (PMID 39835780, 2025). "ApoE-null mice with platelet-specific Jak2 deletion were used to show that Jak2 in platelets plays a critical role in regulating atherosclerosis." (PMID 40825505, 2025). "In ApoE−/− mice, which serve as a dual model for atherosclerosis and AD, the administration of CA markedly improved spatial memory and reduced hippocampal Aβ burden, while simultaneously decreasing systemic and cerebral inflammation." (PMID 40870473, 2025). "After 12 weeks western diet feeding, hIGFREO/ApoE−/− developed significantly less atherosclerosis in the thoraco-abdominal aorta, aortic arch, and aortic sinus, compared with ApoE−/− littermates." (PMID 40171617, 2025).